INS (insulin)
Diseases named in the same sentence as INS in open-access papers (continued):
Sharing a sentence is not in itself a finding about the gene and the disease.
diabetic nephropathy (268 papers, 2010 to 2026). "Genetic factors, such as polymorphisms in genes related to insulin signaling, can also influence the risk of developing diabetic nephropathy." (PMID 40698245, 2025). "Insufficient insulin secretion was one of the risk factor of diabetic nephropathy; 5-methoxytryptophan (5-MTP), acetylcarnitine, taurine and tiglylcarnitine, were strongly correlated with the development of CKD." (PMID 36936143, 2023). "The DCCT confirmed the importance of intensive insulin therapy versus conventional insulin therapy in improving glycemic levels and reducing the risk of diabetic nephropathy, retinopathy, and neuropathy, as well as long-term adverse cardiovascular outcomes." (PMID 37794113, 2023). "In comparison to normal control rats (15.13 ± 0.13μ IU/ml), junk food fed diabetic nephropathy caused rats had a significant decrease in fasting insulin levels (7.04 ± 0.21μ IU/ml)." (PMID 36404830, 2022). "More surprisingly, intensive glycemic control (HbA1C 6.4% vs 7.5%), accomplished by more use of insulin(s) and oral drug combinations is reported to be associated with increased mortality, in particular in T2D patients presenting with diabetic nephropathy." (PMID 32128655, 2020). "Podocytes are insulin-responsive cells of the glomerular filtration barrier and are key in preventing albuminuria, a hallmark feature of diabetic nephropathy." (PMID 28852804, 2017). "Defects in insulin signalling have been implicated in diabetic nephropathy at the level of the IR and IRS proteins." (PMID 27514532, 2016). "Early intensive insulin treatment prevents the increase in renal cortical P38 activity in diabetic rats, thereby attenuating the pathological changes associated with diabetic nephropathy." (PMID 24734256, 2014). "As diabetic nephropathy progresses, db/db mice may manifest weight loss, which could be due to exacerbated insulin resistance and declining pancreatic β-cell function." (PMID 38890983, 2024). "Diabetic nephropathy is the most common cause of dialysis induction, and high blood glucose levels increase triglycerides as the liver is more likely to produce triglycerides from excess sugar and insulin." (PMID 38256336, 2023). "Furthermore, in insulin-treated diabetic patients, an increase in intra-erythrocytic spermidine content has been linked to both diabetic nephropathy and severe retinopathy." (PMID 36771224, 2023). "Regarding miR‐21 predicted target genes, overexpression of miR‐21 may be associated with beta cell death, diabetic nephropathy, inflammatory responses, impaired insulin production or secretion, and T‐cell cytotoxicity, all of which are important in the initiation and progression of T1DM." (PMID 40041782, 2025). "Regarding miR‐21 predicted target genes, its overexpression may be associated with beta cell death, diabetic nephropathy, inflammatory responses, impaired insulin production or secretion, and T‐cell cytotoxicity, which are important in the initiation and progression of T1DM." (PMID 40041782, 2025). "Insulin treatment can increase the level of autophagy and reduce glomerular-associated pathological changes and podocyte injury, suggesting that the increased level of autophagy may help delay the progression of diabetic nephropathy." (PMID 33881140, 2021). "Patient's younger age, the need for insulin therapy, and the presence of DR are strong predictive markers for diabetic nephropathy." (PMID 41598592, 2026). "Insulin therapy protects against diabetic nephropathy by: (i) augmenting renal NEP activity, (ii) reducing Arg-2-mediated injury, and (iii) attenuating tubular damage as evidenced by decreased urinary KIM-1 and NEP fragment shedding." (PMID 41601953, 2026). "Outside the kidney, O‐GlcNAc modification can indirectly contribute to the progression of diabetic nephropathy through regulating insulin sensitivity and insulin secretion." (PMID 39279604, 2025).
diabetic nephropathy (continued). "When insulin signaling is defective, podocytes begin to malfunction, and their number decreases, a characteristic sign of diabetic nephropathy." (PMID 40698245, 2025). "It has been demonstrated that PPARG agonists, such as thiazolidinediones, enhance renal outcomes in diabetic nephropathy by increasing insulin sensitivity, lowering inflammation, and lowering albuminuria." (PMID 40435181, 2025). "Understanding the connections between insulin signaling, metabolic disturbances, and renal injury is crucial for developing successful treatments for diabetic nephropathy." (PMID 40698245, 2025). "Randomized controlled trials have shown that intensive insulin therapy reduces microvascular complications, particularly diabetic kidney disease." (PMID 41011236, 2025). "Contrary to our results, EGFR inhibitor ameliorates the progression of diabetic nephropathy and enhances pancreatic insulin production, resulting in preserved β-cell function and reduced systemic oxidative stress." (PMID 41189666, 2025). "The coagulation and vascular endothelial factors in patients with diabetic nephropathy change with blood glucose levels, influenced by plasma glucose and insulin levels, in turn affecting the body’s coagulation and vascular endothelial function." (PMID 40083378, 2025). "This expert opinion covers the following topics: (a) treatment options and glycemic targets, (b) insulin regimens, (c) T2DM associated with cardiovascular disease, and (d) diabetic kidney disease." (PMID 41299307, 2025). "During the development of diabetic nephropathy, significant damage occurs as insulin signaling function decreases in the kidney, particularly affecting podocytes." (PMID 40698245, 2025). "Numerous studies have provided evidence supporting the effectiveness of intensive insulin therapy in postponing the onset and progression of diabetic nephropathy among type 1 and type 2 diabetic individuals." (PMID 39295783, 2024). "Glucose-lowering drugs such as insulin and incretin-based therapies, exert a well-known renal protective role in diabetic kidney disease, mainly acting at the glomerular level." (PMID 39167349, 2024). "Univariate logistic regression revealed hsa-miR-221 to be a significant predictor of the development of diabetic nephropathy in diabetic patients, along with HbA1c, fasting glucose, fasting insulin, HOMA IR, and BMI." (PMID 37831346, 2023). "Liposome-embedded SOD or SOD mimics improved glucose tolerance and insulin sensitivity in diet-induced obese mice and diabetic rats, attenuated the progression of diabetic nephropathy in T2D mice, and protected β-cells from oxidative damage." (PMID 37237860, 2023). "The potential interaction between dapagliflozin and insulin warrants further investigation to fully elucidate the mechanism of action of SGLT2 inhibitors in diabetic kidney disease." (PMID 36986825, 2023). "Another aspect that relates to the interaction of insulin–IR in the kidneys is the presence of proteinuria, such as albumin, which represents it as a distinct feature of diabetic kidney disease." (PMID 37675359, 2023). "In diabetic nephropathy, the mean levels of BMI, serum fasting insulin, serum fasting glucose, HOMA IR, serum HbA1c, serum creatinine, and ACR exhibited significantly higher mean levels." (PMID 37831346, 2023). "DPP-4inhibitors (insulin-based therapy), a new class of hypoglycemic agents for clinical practice, their role in diabetic nephropathy, with a particular focus on renal protection and alternative markers of cardiovascular disease." (PMID 37538798, 2023). "By using the logistic regression, hsa-miR-221 was found to be a significant predictor of the development of diabetic nephropathy in diabetic patients, along with HbA1c, fasting glucose, fasting insulin, HOMA IR, and BMI." (PMID 37831346, 2023). "This work aims to investigate the therapeutic effect of ursolic acid (UA) plus insulin (In) on diabetic nephropathy (DN) in streptozotocin (STZ)-induced T1DM rats." (PMID 36249783, 2022).
diabetic nephropathy (continued). "LncRNA AK044604 (regulator of insulin sensitivity and autophagy, Risa) and autophagy-related factors Sirt1 and GSK3β play important roles in diabetic nephropathy (DN)." (PMID 35614465, 2022). "In this model, long‐term (>3 month) treatment with rapamycin in the diet improves systemic insulin sensitivity and reduces diabetic nephropathy despite elevating diabetic hyperglycemia." (PMID 35986566, 2022). "For example, in diabetic kidney disease, Insulin or VEGF signaling‐induced AKT phosphorylation and protected kidneys via anti‐apoptosis and anti‐inflammatory effects in podocytes." (PMID 35748097, 2022). "In the AWARD-7 trial for example, dulaglutide compared to insulin treatment resulted in similar effects on HbA1c but reduced the rate of eGFR decline and the risk of ESKD in patients with diabetic kidney disease." (PMID 35496307, 2022). "The focus of the different studies was on insulin sensitivity, the effect on macrophage polarization and on diabetic nephropathy." (PMID 33407530, 2021). "In animal models of IR, rosiglitazone decreased plasma glucose, insulin, and triglyceride levels and also attenuated or prevented diabetic nephropathy and pancreatic islet cell degeneration." (PMID 35096302, 2021). "At that time, it was decided to tentatively treat her diabetic nephropathy mainly, with intensified insulin therapy, ACEI, and diuretics, with close monitoring of her disease progression." (PMID 34664831, 2021). "For example, 5-HT3RA tropisetron shows renal protective effect on early diabetic nephropathy and improves pancreas function, increases insulin synthesis and secretion, and attenuates pancreas apoptosis in streptozotocin-induced diabetic rats." (PMID 33967787, 2021). "The model used in this study was developed around the medical costs for patients undergoing insulin treatment with a focus on diabetic nephropathy, dialysis, and cardiovascular disease, all of which entail high medical costs." (PMID 32940613, 2020). "The novelty of our new findings is due to linagliptin’s effects on insulin signalling, preventing podocyte apoptosis in diabetic nephropathy." (PMID 32238837, 2020). "Among 25 hemodialysis patients with end-stage renal failure due to diabetic nephropathy, 20 (80%) were on insulin treatment, 1 (4%) patient was treated with sulphonylurea in monotherapy, while others (16%) were on diet." (PMID 33269015, 2020). "In diabetic kidney disease, there is progressive glomerular dysfunction and recent studies have demonstrated that the kidney podocyte is a direct target for insulin action." (PMID 33458251, 2020). "Despite the ineffectiveness of increased OST48 to protect against the development of diabetic kidney disease, we did however observe benefits on insulin secretion, fasting insulin and insulin sensitivity by globally elevating OST48 in diabetic mice." (PMID 31541173, 2019). "Most notably, treatment with hrANXA1 re-establishes normal insulin signaling and attenuates the development of hepatosteatosis and diabetic nephropathy." (PMID 30972066, 2019). "Women that consumed caffeine were more likely to be treated with insulin, had less diabetic kidney disease, and a lower ratio of polyunsaturated/saturated fatty acids intake." (PMID 30294299, 2018). "We aim to explore the relationships between oxidative stress, diabetic nephropathy (DN) and short-term insulin pump intensive therapy (insulin therapy)." (PMID 29433562, 2018). "Saponins also were found in the dill extract and have numerous pharmacological properties such as motivation of insulin and C-peptide secretion, antioxidant activity, inhibition of AGEs formation, and also declining of diabetic nephropathy." (PMID 28182107, 2017). "We have also subsequently reported that, in OLETF rats with overt diabetic nephropathy accompanied with massive proteinuria, the stimulatory effect of insulin on renal proximal sodium reabsorption was preserved." (PMID 27247938, 2016).
diabetic nephropathy (continued). "In particular, patients with diabetic nephropathy on CAPD with intraperitoneal insulin have been shown to have a rare pattern of fat deposition that can be seen on computed tomography (CT) and magnetic resonance imaging (MRI)." (PMID 27998312, 2016). "Regarding creatinine clearance and urinary albumin excretion as early signs of diabetic nephropathy, insulin implants were able to correct the functional abnormalities described in the STZ-rat model." (PMID 27253523, 2016). "The role of insulin signaling in the development and progression of diabetic nephropathy has been addressed only recently, mostly due to the relatively recent evidence of the critical role of the pathway in normal kidney function." (PMID 27434075, 2016). "Recent research confirmed that MDG-1, a polysaccharide from O. japonicas, activates the PI3K/Akt signaling pathway and improves insulin sensitivity in a diabetic KKAy mouse model, but little is known about its effects on diabetic nephropathy." (PMID 26393572, 2015). "As the insulin downstream effector, the deficiency of GLUT4 was considered closely related to the function of podocyte in diabetic nephropathy mice." (PMID 25183970, 2014). "Conversely, adoptive transfer of Tregs into leptin receptor null mice improved their insulin sensitivity and diabetic nephropathy." (PMID 23936084, 2013). "Concerning insulin therapy, the advantages of intraperitoneal insulin administration include a higher physiological effect of insulin in patients with diabetic nephropathy during continuous ambulatory PD (CAPD) or automated PD (APD) treatment." (PMID 22013524, 2011). "Downregulation of IGF1R improved insulin response in diabetic mice and alleviated inflammation of diabetic kidney disease in mice In this study IGF1R was significantly increased when comparing healthy controls and prediabetics, and also when comparing prediabetic with diabetic patients." (PMID 40533788, 2025). "The triglyceride-glucose-body mass index (TyG–BMI), an alternative IR index independent of insulin, was identified as an independent risk factor for diabetic kidney disease (DKD)." (PMID 40909885, 2025). "In particular, established diabetic nephropathy treatments, including angiotensin-converting enzyme inhibitors, angiotensin receptor blockers, insulin therapy, and metabolic disorder medications, have been investigated for their potential roles in modulating ferroptotic processes." (PMID 40276370, 2025). "20(R)-Rg3 treatment not only attenuated fasting blood glucose (FBG) levels and advanced glycation end products (AGEs) levels but also improved insulin (INS) levels, blood lipids, oxidative stress, and renal function by regulating MAPKs and NF-κB signal pathways in diabetic nephropathy mice." (PMID 38957183, 2024). "Additionally, endogenous protective factors such as antioxidant enzymes, insulin, and vascular endothelial growth factor are suggested to be involved in the prevention of diabetic nephropathy." (PMID 38664793, 2024). "The clearance of insulin can beadversely altered in patients with diabetic nephropathy/CKD." (PMID 38224978, 2024). "Notably, in these exogenous-insulin treated patients, diabetic nephropathy is accompanied by higher levels of fasting C-peptide." (PMID 37959313, 2023). "Studies have shown that the inability of podocytes to respond to insulin may partially account for the decreased number of podocytes observed in early diabetic nephropathy in diabetic mice." (PMID 37770895, 2023). "This leads to the hypothesis that diabetic nephropathy emerges when insulin secretion is greater than normal." (PMID 37959313, 2023). "This may be because the ADIPOQ rs182052 A allele is related to lower serum adiponectin levels, higher body mass index, higher fasting insulin, thicker skinfold thickness, lower homeostasis model assessment of insulin sensitivity, and diabetic nephropathy." (PMID 37175838, 2023).
diabetic nephropathy (continued). "From this perspective, it can be expectable that in our cohort, insulin users could have significantly higher prevalence of most morbidities and organ complication, including diabetic nephropathy with resultant CKD." (PMID 37196125, 2023). "Increased levels of [18F]FDG and [18F]FTHA in obese insulin resistant mice could be used clinically as an indicator of poor metabolic control, and a complementary test for incipient diabetic nephropathy." (PMID 36787333, 2023). "Therefore, the current research assessed REO's potential benefits on the biochemical, histological, and immunohistochemical alterations of diabetic nephropathy and compared its effects to insulin or their combination in male albino rats." (PMID 37016650, 2023). "The polymorphism rs1801282 (c.34C>G) in codon 12 of the PPARγ2 gene, which results in the substitution of Proline with Alanine (Pro12Ala), was found to be related to higher insulin sensitivity and diminished risk of T2DM and diabetic nephropathy as well as CAD and NAFLD." (PMID 35547362, 2022). "In addition, increased ACR in akr1a1a zebrafish mutants led to insulin resistance and consequently to diabetic retinopathy and diabetic nephropathy." (PMID 35114580, 2022). "In a clinical study of T1D patients, it was shown that those with a complete loss of insulin-producing cells and no C-peptide were more prone to the development of diabetic nephropathy." (PMID 34944607, 2021). "Our results suggest that tightly balanced insulin action targeting podocyte Orai1 is critical for maintaining filter integrity, which provides novel perspectives on therapeutic strategies for proteinuric diseases, including diabetic nephropathy." (PMID 34764278, 2021). "Above all, in order to understand the effect of oxidative stress on diabetic nephropathy and to further precede the clinical valid treatment measures, we monitored the level of oxidative stress of patient in different stages of diabetic nephropathy before and after insulin pump therapy." (PMID 29433562, 2018). "Thus, we aimed to further investigate podocyte insulin responses early in the context of diabetic nephropathy." (PMID 28852804, 2017). "One patient in the NPH insulin treatment group had diabetic nephropathy (microalbuminuria)." (PMID 27887605, 2016). "It is unknown whether autophagy activity is altered in insulin resistant podocytes and whether autophagy could be a therapeutic target for diabetic nephropathy (DN)." (PMID 27077005, 2016). "We hypothesize that blunted autophagy activity in insulin resistant podocyte is one of the mechanisms that accounts for the podocytes injury in the pathogenesis of diabetic nephropathy." (PMID 27077005, 2016). "Suppression of the insulin-induced overexpression of SGLT2 in tubular cells might be a novel therapeutic strategy for the treatment of diabetic nephropathy." (PMID 26023321, 2015). "We hypothesize that perturbed insulin-Akt cascade in DM leads to alterations in trafficking of megalin and cubilin, which results in urinary cubilin shedding as a prelude to MA in early diabetic nephropathy." (PMID 26465605, 2015). "Taurine may act as a regulator of insulin secretion, and hence the protective effect of taurine on diabetic nephropathy may be accomplished by blood glucose lowering through improved insulin secretion." (PMID 24707287, 2014). "Insulin stimulates the production of insulin-like growth factory 1 (IGF-1) by vascular smooth muscle cells and other cell types, which have been implicated in the development of diabetic kidney disease." (PMID 23690758, 2013). "Diabetic nephropathy patients only show gender differences and increased use of insulin." (PMID 22905926, 2012). "Moreover, in this cohort, the presence of diabetic nephropathy may have necessitated the discontinuation of metformin and introduction of insulin but these also biased the findings to vildagliptin." (PMID 39186745, 2024).